MAP4K3 (mitogen-activated protein kinase kinase kinase kinase 3)
Description:
Serine/threonine kinase that plays a role in the response to environmental stress. Appears to act upstream of the JUN N-terminal pathway. Activator of the Hippo signaling pathway which plays a pivotal role in organ size control and tumor suppression by restricting proliferation and promoting apoptosis. MAP4Ks act in parallel to and are partially redundant with STK3/MST2 and STK4/MST2 in the phosphorylation and activation of LATS1/2, and establish MAP4Ks as components of the expanded Hippo pathway.
Synonyms: GLK; MEKKK 3; RAB8IPL1; MAPKKKK3; MEKKK3
Tractability: Small molecule: a structure with a bound ligand is known; a high-quality ligand is known; it belongs to a druggable protein family. PROTAC: it is named in the literature on targeted protein degradation; ubiquitination databases record sites on it; its protein half-life has been measured; a small molecule that binds it is known.
Target class: Protein Kinase; STE protein kinase STE20 family; STE protein kinase group; Enzyme; Kinase; STE protein kinase KHS subfamily
Gene: Protein-coding gene on chromosome 2 (39,249,266 to 39,437,324, reverse strand). Ensembl gene ENSG00000011566.
Subcellular location (Human Protein Atlas): Centriolar satellite
Gene Ontology:
Molecular function: ATP binding; protein binding; protein serine kinase activity; protein serine/threonine kinase activity; MAP kinase kinase kinase kinase activity; protein kinase activity
Biological process: intracellular signal transduction; protein phosphorylation; response to tumor necrosis factor; response to UV; JNK cascade
Cellular component: cytoplasm
Genetic constraint (gnomAD): Loss-of-function variants: 33 observed, 55.7 expected, observed/expected ratio (o/e) 0.59, 90% interval 0.45 to 0.79. The upper end of that interval is the gene's LOEUF score, 0.79, which puts it in group 3 of 6, group 1 being the genes least tolerant of losing a copy. Missense variants: 573 observed, 590.3 expected, observed/expected ratio (o/e) 0.97, 90% interval 0.91 to 1.04. Synonymous variants: 234 observed, 202.72 expected, observed/expected ratio (o/e) 1.15, 90% interval 1.04 to 1.29.
Homologues: Orthologues: chimpanzee MAP4K3 (99% identical), macaque MAP4K3 (99% identical), dog MAP4K3 (98% identical), pig MAP4K3 (98% identical), guinea pig MAP4K3 (97% identical), rat Map4k3 (96% identical), mouse Map4k3 (96% identical), rabbit MAP4K3 (95% identical), tropical clawed frog map4k3 (90% identical), zebrafish map4k3a (81% identical), zebrafish map4k3b (75% identical), Caenorhabditis elegans gck-2 (40% identical). Paralogues in human: MAP4K5 (66% identical), MAP4K2 (52% identical), MAP4K1 (44% identical), MAP4K4 (30% identical), TNIK (29% identical), MINK1 (29% identical), NRK (23% identical), SLK (23% identical), STK10 (22% identical), TAOK1 (22% identical), TAOK3 (20% identical), TAOK2 (19% identical), and 23 more.
Diseases named in the same sentence as MAP4K3 in open-access papers:
MAP4K3 is named in the same sentence as 47 diseases in open-access papers, as found by Europe PMC text mining. Sharing a sentence is not in itself a finding about the gene and the disease. The quoted sentences say what the papers report.
autoimmune disease (7 papers, 2018 to 2023). A disorder resulting from loss of function or tissue destruction of an organ or multiple organs, arising from humoral or cellular immune responses of the individual to their own tissue constituents. "Previous studies have demonstrated that MAP4K3 expression levels are significantly increased in peripheral blood T cells from patients with autoimmune diseases such as RA, SLE and adult-onset Still’s disease." (PMID 36891318, 2023). "In addition to potential modulation of MAP4K3 as a treatment for autoimmune disease, there are many disorders believed to involve over-activation of mTORC1, including various cancers and certain neurological diseases." (PMID 37221017, 2023). "Moreover, MAP4K1 downregulation and MAP4K3 overexpression in T cells are involved in human autoimmune diseases such as psoriatic arthritis, rheumatoid arthritis (RA), adult-onset Still’s disease, and SLE." (PMID 31766293, 2019). "MAP4K3 inhibition could thus prove to be a highly effective therapy for diseases where enhanced autophagy activation would be beneficial, including neurodegenerative disorders, lysosomal storage diseases, and possibly autoimmune disorders." (PMID 29507340, 2018).
hepatocellular carcinoma (7 papers, 2016 to 2025). A malignant tumor that arises from hepatocytes. "Researchers also observed that the downregulation of miR-186-5p attenuated the tumor suppressor effect of MAP4K3 knockdown in hepatocellular carcinoma cells." (PMID 35356290, 2022). "In conclusion, researchers revealed that LINC00665 could upregulate MAP4K3 expression by sponging miR-186-5p, thereby promoting the progression of hepatocellular carcinoma." (PMID 35356290, 2022). "Also, LINC00665 was proven to display high expression in hepatocellular carcinoma cells and tissues, and could facilitate cell viability and autophagy while suppressing cell apoptosis via miR-186-5p/MAP4K3 axis in hepatocellular carcinoma." (PMID 35101035, 2022). "In addition, MAP4K3 depletion inhibited cell viability and induced apoptosis and autophagy, indicating that MAP4K3 may act as an oncogene in the progression of hepatocellular carcinoma." (PMID 35356290, 2022). "In hepatocellular carcinoma, LINC00665 modulates viability, apoptosis, and autophagy through sponging miR-186-5p and regulating MAP4K3." (PMID 33407473, 2021).
breast carcinoma (5 papers, 2014 to 2023). "The calcineurin regulatory subunit PPP3R1 shows elevated expression in ER− breast cancer, whereas positive regulators of Rag C/D, including folliculin complex members FLCN and FNIP1, along with MAP4K3, are decreased in ER− breast cancer patients." (PMID 36372230, 2022). "Several previous studies investigated RICTOR and MAP4K3, both of which are our proposed drug targets for breast cancer." (PMID 26336805, 2015). "Computationally, PTPRF, PRKAR2B, MAP4K3, and RICTOR were calculated as highly drug-targetable genes for breast cancer." (PMID 26336805, 2015). "Selective knockdown of MAP4K3 by siRNA leads to a significant reduction in cell viability in five paediatric glioma cell lines as assayed by CellTiter Glo, an effect not seen in 18/20 breast cancer cells (p = 0.0017, pHGG vs breast cancer, t-test)." (PMID 24548782, 2014).
non-small cell lung carcinoma (5 papers, 2014 to 2024). A group of at least three distinct histological types of lung cancer, including non-small cell squamous cell carcinoma, adenocarcinoma, and large cell carcinoma. "Down-regulated hsa-let-7c was significantly associated with metastasis and poor survival of patients, and hsa-let-7c inhibits cancer metastasis by degrading ITGB3 and MAP4K3 in non-small cell lung cancer." (PMID 26933913, 2016). "Additionally, circ-RAD23B has been found to impede the progression of non-small cell lung cancer by modulating the miR-142-3p/MAP4K3 axis." (PMID 38289973, 2024).
systemic lupus erythematosus (5 papers, 2018 to 2025). An autoimmune multi-organ disease typically associated with vasculopathy and autoantibody production. "AhR–ROR-γt complex is a therapeutic target for MAP4K3/GLKhighIL-17Ahigh subpopulation of systemic lupus erythematosus." (PMID 31318609, 2019). "Furthermore, MAP4K3 loss-of-function renders KO mice resistant to experimental autoimmune encephalitis, and human patients with systemic lupus erythematosus display increased expression of MAP4K3 accompanied by hyperactivation of Protein Kinase C-θ." (PMID 37221017, 2023).
glioma (4 papers, 2014 to 2026). A benign or malignant brain and spinal cord tumor that arises from glial cells (astrocytes, oligodendrocytes, ependymal cells). "RagC- and Map4K3-deficient glioma cells had significantly increased proliferation and showed altered morphology and motility." (PMID 41865271, 2026). "The PTEN-regulating miR-26a is amplified in high-grade glioma and miR-26a potently induced apoptosis and downregulated the expressions of MAP4K3." (PMID 36101325, 2022). "RagC and Map4K3 knockout in glioma cells was generated using CRISPR-Cas and shRNA." (PMID 41865271, 2026). "In the context of pHGG, although the kinase domain is not retained in the fusion, MAP4K3 plays some functional role as selective knockdown by siRNA leads to a significant and selective reduction in cell viability in paediatric glioma cell lines." (PMID 24548782, 2014).
lung carcinoma (4 papers, 2017 to 2025). "The interaction of MAP4K3 and IQGAP1 was associated with poorer prognosis in lung cancer, indicating the importance of IQGAP1-mediated signaling." (PMID 34439095, 2021). "Other than Wnt signaling, MAP4K3, a member of the mitogen-activated protein kinase kinase kinase kinase (MAPK4) family, regulates lung cancer metastasis through IQGAP1." (PMID 34439095, 2021). "Furthermore, transgenic overexpression of MAP4K3 significantly promoted distant metastasis in a lung cancer mouse model, whereas the absence of IQGAP1 completely abolished MAP4K3-induced lung metastasis." (PMID 41034525, 2025).
pancreatic cancer (4 papers, 2014 to 2022). "Mutation in the MAP4K3 gene sequence was predicted to modulate cancer progression, and this hypothesis was supported by abnormal levels of MAP4K3 expression in pancreatic cancer tissues and enhanced cellular proliferation by RNAi-induced suppression of MAP4K3." (PMID 25313363, 2014). "There is date showed that MAP4K3 as a novel apoptosis inducer which modulates cell death via the post-transcriptional regulation of BH3-only proteins in pancreatic cancer.We reported that MAP4K3 promotes HCC cell migration and invasion." (PMID 28099144, 2017). "Clinico-pathological analyses showed that 17.4% of surgical pancreatic cancer specimens were quadruple-positive for IGF-1R, EP2 (or EP4), MAP4K3, and PKC-θ." (PMID 25638159, 2015). "To assess the physiological relevance of our in vivo observations, we examined the expression patterns of IGF-1R, EP2/EP4, MAP4K3, and PKC-θ in surgical specimens from pancreatic cancers based on immunohistochemical analyses." (PMID 25638159, 2015). "According to these analyses, 17.4% of the cases were quadruple-positive for IGF-1R, EP2/EP4, MAP4K3, and PKC-θ, indicating that crosstalk may occur between these signaling pathways in human pancreatic cancers." (PMID 25638159, 2015). "In pancreatic cancer cells, MAP4K3 knockdown cells failed to phosphorylate PKCθ, and inhibition of PKCθ activity suppressed insulin-like growth factor-1-mediated cell growth and viability, indicating that the MAP4K3/PKCθ axis may be a therapeutic target for pancreatic cancer." (PMID 36358843, 2022).
Hypertension (2 papers, 2021 to 2022). The presence of chronic increased pressure in the systemic arterial system. "Thus, MAP4K3/GLK may be involved in the pathogenesis of coronavirus infection, hypertension, diabetes, or cardiovascular diseases." (PMID 35894122, 2022).
astrocytomas (1 paper, 2026). "High-grade astrocytomas had significantly reduced immunoreactivity for RagC and Map4K3 compared to low-grade astrocytomas." (PMID 41865271, 2026).
chronic liver failure (1 paper, 2025). Liver failure that develops slowly and gradually for some time, possibly for years, often as the result of cirrhosis, or malnutrition. "Furthermore, recent investigations have highlighted the potential of exosomes derived from human BM-MSCs, which contain let-7a-5p, in promoting autophagy by targeting MAP4K3 in models of acute-on-chronic liver failure." (PMID 41390431, 2025).
Insulin resistance (1 paper, 2022). Increased resistance towards insulin, that is, diminished effectiveness of insulin in reducing blood glucose levels. "Moreover, MAP4K3 is associated with insulin resistance in obese mice." (PMID 35510516, 2022).
melanoma (1 paper, 2017). A malignant, usually aggressive tumor composed of atypical, neoplastic melanocytes. "Along with targeting other oncogenic target genes such as SODD, SMAD1, and MAP4K3, miR-26a inhibited the growth of melanoma cells by directly downregulating MITF." (PMID 28698805, 2017). "In addition, this study showed that miR-26a reduced the expression of MAP4K3 in both melanoma cell lines." (PMID 28698805, 2017). "Results showed that miR-26a mimics remarkably reduced the expressions of MITF and MAP4K3 in both SKMEL-28 and WM1552C melanoma cell lines." (PMID 28698805, 2017).
multiple system atrophy (1 paper, 2020). Multiple system atrophy (MSA) is a neurodegenerative disorder characterized by autonomic failure (cardiovascular and/or urinary), parkinsonism, cerebellar impairment and corticospinal signs with a median survival of 6-9 years. "Another research group performed circRNA sequencing of the brain samples from multiple system atrophy (MSA) patients and identified five circRNAs, namely IQCK, MAP4K3, EFCAB11, DTNA, and MCTP1, that were overexpressed in the white matter of the cortical tissue." (PMID 33269108, 2020).
prostate carcinoma (1 paper, 2012). A carcinoma that arises from epithelial cells of the prostate gland. "Our screen also identified other stress kinases, including MAP3K7, MAP4K3, and MAPKAPK5 (data not shown), which underscores the critical nature of stress kinase signaling in regulating prostate cancer cell growth." (PMID 22761715, 2012).
psoriasis (1 paper, 2020). An autoimmune condition characterized by red, well-delineated plaques with silvery scales that are usually on the extensor surfaces and scalp. "Psoriasis-associated plasma miRNAs target MAP kinases; it has been reported that miR-148a-3p targets MAPK1, MAP2K3, MAP3K4, and MAP4K3." (PMID 32411787, 2020).
small cell lung carcinoma (1 paper, 2021). Small cell lung cancer (SCLC) is a highly aggressive malignant neoplasm, accounting for 10-15% of lung cancer cases, characterized byrapid growth, and early metastasis. "Regarding to small cell lung carcinoma (NSCLC), the blockade of MAP4K3 inhibited tumor progression." (PMID 33669949, 2021).
thyroid (1 paper, 2016). "TCF12, KDM5C, IGF2BP3 and MAP4K3 mutations newly identified in our study might possibly be follicular tumor-specific thyroid mutations." (PMID 27626165, 2016).
thyroid cancer (1 paper, 2016). "By contrast, somatic mutations of TCF12, KDM5C, IGF2BP3 and MAP4K3 have not been reported in any types of thyroid cancers." (PMID 27626165, 2016).
tongue cancer (1 paper, 2015). A malignant neoplasm affecting the tongue. "After comparison between tongue cancer and corresponding normal samples, GNA15, PPP2R3A, LAMB3, HSPA2, and MAP4K3 were identified as five top-ranking genes." (PMID 26336805, 2015).
cancer (24 papers, 2014 to 2025). A tumor composed of atypical neoplastic, often pleomorphic cells that invade other tissues. "The overexpression of MAP4K3 has been associated with cancer recurrence and poor prognosis in various malignancies." (PMID 41034525, 2025). "Further, MAP4K3 regulates mTORC1 signaling, impacting cell survival, and contributes to drug resistance by helping cancer cells adapt to metabolic stress." (PMID 40362400, 2025). "For example, hsa-miR-183-5p was found to inversely regulate PTPN4, serving as a therapeutic target to suppress the metastatic potential in NSCLC patients, and hsa-let-7c-5p was verified to prevent cancer metastasis by degrading its bridging hub ceRNA, MAP4K3." (PMID 36084156, 2022). "Ocoxin also downregulates the MAPK signaling proteins implicated in cancer development, such as MAP3K9 and MAP4K3." (PMID 33669949, 2021). "In our study, decreased levels of MAP4K3 achieved using siRNA or transfection of two miRNAs increase the sensitivity of cancer cells to sorafenib, thereby resulting in the inhibition of cell growth, migration and invasion." (PMID 28099144, 2017). "Our results showed that genes CACNG6, DUSP6 and MAP4K3 in the MAPK pathway have reorganized spatial structures in MM, and associate with gene expression regulation as well as epigenetic mark changes, which might contribute to cancer development." (PMID 29203764, 2017). "We computationally predicted PTPRF, PRKAR2B, MAP4K3, and RICTOR to be responsible for the cancer phenotype, and each of them was experimentally validated by means of cell death or migration assay." (PMID 26336805, 2015). "MiRNA-let-7c-5p, the miRNA studied in our research, has been widely reported in different cancer types, it can mediate the pathogenesis progression of NSCLC by targeting ITGB3 and MAP4K3 31, and promote the sensitivity of LUAD cells to EGFR-TKIs by inhibiting the WNT pathway." (PMID 36046641, 2022). "Taken together, targeting MAP4K3 (GLK) may be useful for treating/preventing autoimmune disease, cancer metastasis/recurrence, and aging." (PMID 31640697, 2019). "MAP4K3 is not frequently mutated in HNSCC (1.6%), but the mutation found in UM-SCC-17B (V322M) is identical to that identified in three cases of the Cancer Cell Line Encyclopedia (CCLE)." (PMID 25275298, 2014).
tumor (9 papers, 2014 to 2025). "MAP4K3 has been associated with several malignancies in both an oncogenic and tumour suppressor capacity." (PMID 24548782, 2014). "IND as a KP inhibitor reverses the effects of TRP depletion in the tumor microenvironment, which results in the reactivation of MAP4K3 and subsequent activation of mTORC1 activity, together with the inactivation of GCN2 kinase in T helper cells." (PMID 38201550, 2023). "The tumour-bearing group had increased serum WF content, and the skeletal-muscle showed a reduction in IRS-1 and RAG activation, increased PKB/Akt and Erk/MAP4K3 on the 21st day, and maintenance of p70S6K1, associated with increases in muscle STAT-3 and STAT-6 levels in these tumour-bearing rats." (PMID 30975087, 2019). "Thus we hypothesise that the DHX57:TMEM178:MAP4K3 is activating as disruption of the protein would otherwise seem incompatible with tumour cell growth and proliferation." (PMID 24548782, 2014).
infection (1 paper, 2009). The state of being infected such as from the introduction of a foreign agent such as serum, vaccine, antigenic substance or organism. "Transcripts for the GMPS and MAP4K3 genes showed significant breed differences post-infection where the trypanotolerant N'Dama had higher levels of expression." (PMID 19409086, 2009). "Despite the higher endogenous levels in Boran before infection, N'Dama had significantly higher expression levels of MAP4K3 mRNA at 25, 29 and 34 dpi relative to Boran perhaps indicating a heightened response to stress in trypanotolerant cattle." (PMID 19409086, 2009).
MAP4K3 also shares sentences with these, for which no sentence is quoted: adult-onset Still disease (4 papers); rheumatoid arthritis (3); autism (1); autoimmune encephalitis (1); Autoimmunity (1); Crohn disease (1); diabetes (1); epilepsy (1); gestational diabetes (1); keratosis (1); lysosomal storage disease (1); malignant glioma (1); mental disorder (1); metabolic disorder (1); myeloma (1); neurological diseases (1); Obesity (1); ovarian carcinoma (1); personality disorder (1); pulmonary disorder (1); retinitis pigmentosa (1); schizophrenia (1); Sézary syndrome (1); type 2 diabetes (1).